IGF2BP3 (insulin like growth factor 2 mRNA binding protein 3)
Diseases named in the same sentence as IGF2BP3 in open-access papers (continued):
Sharing a sentence is not in itself a finding about the gene and the disease.
metastatic tumors (3 papers, 2020 to 2023). "In the LUAD dataset GSE126548, only IGF2BP3 is significantly up‐regulated in metastatic tumors." (PMID 37171793, 2023). "We did not detect a significant difference in IGF2BP3 expression levels between primary and metastatic tumors." (PMID 32719743, 2020).
myocardial infarction (3 papers, 2023 to 2025). Gross necrosis of the myocardium, as a result of interruption of the blood supply to the area, as in coronary thrombosis. "Functionally, MMP3 acts as a downstream effector of IGF2BP3 to promote heart regeneration and improve cardiac function after myocardial infarction." (PMID 40869184, 2025). "In particular, IGF2BP3 promotes cardiac regeneration and improves cardiac function after myocardial infarction." (PMID 37188676, 2023). "Triphenyltetrazolium chloride (TTC) staining indicated that IGF2BP3 significantly reduced myocardial infarction size, as determined by the increased red-stained area, while Masson trichrome staining showed that it significantly reduced myocardial fibrosis." (PMID 37188676, 2023). "Here we show that IGF2BP3 plays an important role in regulating adult cardiomyocyte proliferation and regeneration in a mouse model of myocardial infarction." (PMID 37188676, 2023). "HIF1α, activated by myocardial infarction (MI)/hypoxia, bound to the FTO promoter to decrease its expression, causing aberrant m6A modification, while FTO-mediated m6A modification of EPRS, regulated by IGF2BP3, played a key role in cardiac fibrosis after MI." (PMID 39869517, 2025).
oral cancer (3 papers, 2017 to 2025). "On the cellular level, it has been reported that IGF2BP3 is specifically overexpressed at the invasive front of invasive OSCC cells and its depletion reduced the invasive capacity of oral cancer cells and impaired tumor growth in a mouse xenograft model." (PMID 32957697, 2020). "Although the detailed mechanisms that drive IGF2BP3 expression in oral cancer remain to be determined, a recent study identified epidermal growth factor (EGF) as an inducer of IGF2BP3 and PDPN expression." (PMID 32957697, 2020). "However, additional studies are required to comprehensively map the RNA and protein interactome of IGF2BP3, and to characterize the function of the other IGF2BP family members in oral cancer." (PMID 32957697, 2020).
psoriasis (3 papers, 2022 to 2024). An autoimmune condition characterized by red, well-delineated plaques with silvery scales that are usually on the extensor surfaces and scalp. "Meanwhile, compared to healthy controls, the mRNA level of IGF2BP3 in psoriasis lesions was upregulated, and the level of HNRNPA2B1 was significantly downregulated." (PMID 38436011, 2024). "Moreover, it can be found from the real-time qPCR result that the mRNA expression of IGF2BP3 in psoriasis lesions are upregulated compared to healthy controls." (PMID 36193416, 2022).
renal carcinoma (3 papers, 2023 to 2024). A carcinoma arising from the epithelium of the renal parenchyma or the renal pelvis. "Furthermore, limited but interesting findings have confirmed that unlike other m6A‐related genes, IGF2BP3 can be detected in the serum of cancer patients, which reveals that serum IGF2BP3 probably can be used as a diagnostic and prognostic marker in prostate and renal cancers." (PMID 36891946, 2023). "Besides, ZMIZ2 was screened to be the target gene regulated by the IGF2BP3/circRARS complex in an m6A-dependent manner in renal carcinoma." (PMID 39266996, 2024).
Sepsis (3 papers, 2022 to 2025). Sepsis is defined as life-threatening organ dysfunction caused by a dysregulated host response to infection. "Meanwhile, GSE100159 dataset manifested that YTHDF1 was downregulated and IGF2BP3 was upregulated in sepsis." (PMID 35508474, 2022). "In the second sepsis datasets, four diseases including sepsis at 1 day and 3 days and sepsis plus shock at 0 day and 7 days shared one RNA methyltransferase PCIF1 and one RNA methylation reader IGF2BP3." (PMID 35211628, 2022).
Alzheimer disease (2 papers, 2020 to 2023). A progressive, neurodegenerative disease characterized by loss of function and death of nerve cells in several areas of the brain leading to loss of cognitive function such as memory and language. "For comparison, voxel-wise analyses for APOE ɛ4 showed only modest focal medial temporal signal, in contrast to the robust Alzheimer’s disease pattern of association seen for the PPP2R2B and IGF2BP3 SNPs identified through GWAS." (PMID 33426524, 2020). "Nevertheless, the import of these potential mechanisms in relation to tau in Alzheimer’s disease is still unclear, and our findings suggest that additional study of the IGF2BP3 locus may be warranted." (PMID 33426524, 2020). "However, individuals with the IGF2BP3 susceptibility allele had higher amyloid load compared to their counterparts even though both groups had similar ages, suggesting that this allele may impact multiple components of the Alzheimer’s disease biomarker cascade." (PMID 33426524, 2020).
anemia (2 papers, 2022 to 2024). A reduction in the number of red blood cells, the amount of hemoglobin, and/or the volume of packed red blood cells. "We then confirmed the overexpression of IGF2BP3 in clinical bone marrow samples of patients with AML compared with those of patients with iron deficiency anemia (IDA), and higher IGF2BP3 expression was indeed correlated with the proliferation and apoptosis of leukemic cells." (PMID 35217832, 2022). "We used the receiver operating characteristic (ROC) curve to measure the potential diagnostic value of insulin-like growth factor 2 mRNA-binding protein 3 (IGF2BP3) mRNA in the prediction of severe anaemia in HbH-CS disease." (PMID 39088431, 2024). "We found that IGF2BP3 has a good predictive value for severe anemia in HbH-CS disease by plotting ROC curves, suggesting that IGF2BP3 may be a biomarker for predicting the severity of HbH-CS disease." (PMID 39088431, 2024).
Arthritis (2 papers, 2025). Inflammation of a joint. "The CIA rat model was used to assess the role of CEL in alleviating arthritis and inhibiting IGF2BP3 expression." (PMID 41164801, 2025). "The IGF2BP3-KO arthritis mice presented decreased arthritis scores and ankle thickness than the WT arthritis mice." (PMID 40355406, 2025). "IGF2BP3 knockout (KO) arthritis mice also showed that the arthritis protective effect of CEL depends on IGF2BP3." (PMID 41164801, 2025). "And, in the K/BxN arthritis model, the IGF2BP3−/− mice exhibited a milder inflammatory state and bone damage." (PMID 40355406, 2025). "In an arthritis model of IGF2BP3−/− mice, IGF2BP3 knockout inhibited RA-FLS proliferation and inflammatory infiltration, and further ameliorated RA joint injury." (PMID 40355406, 2025). "IGF2BP3−/− mice were generated and used to establish an arthritis mouse model by transferring serum from adult arthritis K/BxN mice." (PMID 40355406, 2025). "And IGF2BP3 KO arthritis mice also revealed that the arthritis therapeutic effect of CEL depends on IGF2BP3." (PMID 41164801, 2025). "IGF2BP3 knockout (KO) arthritis mice were used to identify the targets and mechanism of CEL in relieving RA." (PMID 41164801, 2025). "KO‐IGF2BP3 arthritis mice further showed that the protective effect of CEL against arthritis depended on IGF2BP3." (PMID 41164801, 2025). "Compared with those in WT arthritis mice, the expression levels of iNOS, p62 and p-S6K was lower in the synovium of IGF2BP3-KO arthritic mice, which further indicated IGF2BP3 knockdown alleviated RA progression by inhibiting mTORC1 activation and autophagy." (PMID 40355406, 2025). "In addition, compared with those of WT mice with arthritis, the proportions of F4/80+CD11b+CD86+ M1 macrophages were lower in the spleens of IGF2BP3-KO mice with arthritis." (PMID 40355406, 2025). "Genetic deletion of IGF2BP3 attenuated the arthritis score and ankle thickness in arthritic mice." (PMID 41164801, 2025). "Moreover, RASGRF1 and NLRP3 protein expression was lower in the synovial tissue of the IGF2BP3-KO arthritis mice than in that of the WT arthritis mice." (PMID 40355406, 2025). "Then, we generated an arthritis model using IGF2BP3-KO mice." (PMID 40355406, 2025). "In WT arthritis mice, the serum contents of TNF‐α and IL‐6 decreased with CEL treatment; the IGF2BP3 KO group and the IGF2BP3 KO plus CEL group presented the same trend." (PMID 41164801, 2025). "To determine whether IGF2BP3 is the primary target of CEL alleviating RA, we constructed an arthritis model in IGF2BP3 knockout (KO) mice." (PMID 41164801, 2025).
atherosclerosis (2 papers, 2024 to 2025). A disease characterized by the build-up of fatty material and calcium deposition in the arterial wall resulting in partial or complete occlusion of the arterial lumen. "In cardiovascular‐related studies, SNHG12 could interact with DNA‐dependent protein kinase (DNA‐PK) and IGF2BP3 and play a protective role in atherosclerosis and angiogenic endothelial cells' response to ischemia." (PMID 38946724, 2024).
B cell lymphoma (2 papers, 2021 to 2024). "IGF2BP3 exhibits a strong expression in lymphoid malignancies such as B cell lymphomas of a germinal center origin." (PMID 33805930, 2021). "Two large gene expression data sets were probed for the expression of IGF2BP3—the highest levels were seen among the B-cell lymphomas of a germinal center origin and well-established (KMT2A-rearranged and ETV6-RUNX1) and novel subtypes of B-ALL (e.g., NUTM1 and ETV6-RUNX1-like)." (PMID 33805930, 2021).
Barrett esophagus (2 papers, 2019 to 2021). Esophageal lesion lined with columnar metaplastic epithelium which is flat or villiform. "Accordingly, IGF2BP3 is detectable in some premalignant human lesions, including dysplasia in Barrett esophagus, pancreatic intraductal neoplasia, and atypical endometriosis; in addition, many tumor types upregulate IGF2BP3 compared to normal tissue counterparts." (PMID 32010687, 2019).
bile duct cancer (2 papers, 2012 to 2017). "Up-regulated expression of IGF2BP3, NEK2 and HOXB7 mRNA in our study confirms recent reports suggesting detection of tumor-associated gene expression profiles in biliary tract specimens as potentially useful tools in the diagnosis of bile duct cancer." (PMID 22879911, 2012).
bladder urothelial carcinoma (2 papers, 2021 to 2024). "The UALCAN database showed that the transcript level of IGF2BP3 was higher in the primary bladder urothelial carcinoma (n = 408) than that in the normal samples (n = 19) (P = 0.0001)." (PMID 39680264, 2024).
breast tumors (2 papers, 2021 to 2022). "Our approach identified two genes (EN1 and IGF2BP3) that had increased variability in BRCA1-associated breast tumours." (PMID 34287743, 2021). "Of these, two genes (EN1 and IGF2BP3) were significantly variable in both BRCA1-associated and basal-like breast tumours." (PMID 34287743, 2021). "EN1 and IGF2BP3 were variably expressed in both BRCA1-associated and basal-like breast tumours." (PMID 34287743, 2021).
cervical squamous cell carcinoma (2 papers, 2023 to 2024). A squamous cell carcinoma arising from the cervical epithelium. "When any of the m6A readers (IGF2BP2 and IGF2BP3) or m6A writer METTL3 were mutated, BRD9 was significantly highly expressed in cervical squamous cell carcinoma and endocervical adenocarcinoma (CESC), BRCA and LUAD." (PMID 38303608, 2024).
colorectal adenocarcinoma (2 papers, 2015 to 2021). The most common type of colorectal carcinoma. "Although prior investigators have assessed a group of colorectal adenocarcinomas for the presence of IGF2BP3 protein via IHC, a quantitative analysis of these tumors for IGF2BP3 mRNA expression in a sizable population of patients has not yet been carried out." (PMID 26244168, 2015).
cutaneous squamous cell carcinoma (2 papers, 2022 to 2023). "Both IGF2BP3 mRNA and protein levels were found to be upregulated in cutaneous squamous cell carcinoma." (PMID 34894048, 2022).
ductal adenocarcinoma (2 papers, 2010 to 2025). "For example, in an IHC study of 138 invasive ductal carcinomas of the breast, tumors that were histologically high-grade, exhibited tumor necrosis, or were of the TNBC subtype showed significantly increased IGF2BP3 expression, and IGF2BP3 expression was associated with poor patient prognosis." (PMID 40672753, 2025). "In our cohort, 63% of ductal adenocarcinoma showed IGF2BP3 expression." (PMID 20178612, 2010).
endometriosis (2 papers, 2024 to 2026). The growth of functional endometrial tissue in anatomic sites outside the uterine body. "Efects of IGF2BP3 on endometriosis were confrmed in vitro and in vivo." (PMID 38760723, 2024).
fibrosis (2 papers, 2024 to 2025). the formation of excess fibrous connective tissue in an organ or tissue in a reparative or reactive process. "EPRS, negatively affected by FTO via IGF2BP3-mediated m6A modification, was critical in regulating cardiac fibrosis after MI." (PMID 39538146, 2024).
gallbladder carcinoma (2 papers, 2022 to 2023). "Since IGF2BP3 is associated with poor outcomes of gallbladder carcinoma (GBC), we aimed to explore the association between its N6-methyladenosine (m6A) RNA methylation and GBC progression." (PMID 36313631, 2022). "Thus, USP16 stabilizes IGF2BP3, which may be the partial mechanism of MNX1-AS1-driven gallbladder cancer." (PMID 36980227, 2023).
giant cell tumor (2 papers, 2020 to 2024). A benign, intermediate, or malignant tumor that arises from the bone or soft tissue. "It is also remarkable that the expression of Myc is low and of IGF2BP3 is undetectable in the sample of malignant giant cell tumor of bone, which shows high translation activity similar to the aggressive osteosarcomata but is not susceptible to the translation inhibitors tested in this study." (PMID 38561347, 2024).
Insulin resistance (2 papers, 2023 to 2024). Increased resistance towards insulin, that is, diminished effectiveness of insulin in reducing blood glucose levels. "In addition, specifically overexpressing IGF2BP3 in adipocytes by adeno-associated virus serotype Rec2 (AAVRec2) decreased body weight and alleviated insulin resistance in HFD mice." (PMID 38196046, 2024). "Our results demonstrated that IGF2BP3 expression helped reduce body fat ratio, body weight, and alleviate insulin resistance." (PMID 38196046, 2024). "Additionally, the insulin resistance index HOMA-IR was elevated in HFD mice but improved with IGF2BP3 overexpression." (PMID 38196046, 2024).
metastatic cancer (2 papers, 2020 to 2021). A carcinoma which has spread from the original site of growth to another anatomic site. "We observed multiple occurrences of SPRR1B, one of the most significantly down-regulated genes in the IGF2BP3 overexpression group, and one of the most significantly down-regulated genes in metastatic cancer." (PMID 34737950, 2021). "In primary or metastatic cancer, mRNAs IGF2BP3, HOXA9, HOXA10, CEBPG competed with HOXA11-AS mutually, and HOXA10 as well as IGF2BP3 were also continuously up-regulated among normal-primary-metastatic process with significant difference in variance analysis." (PMID 33614509, 2020).
Ovarian Tumor (2 papers, 2019 to 2024). "IGF2BP3 is highly expressed in ovarian mucus tumours and is positively correlated with malignant tumours, indicating that IGF2BP3 can be used for the differential diagnosis and progression monitoring of ovarian tumours." (PMID 38358034, 2024).
pancreatitis (2 papers, 2021 to 2025). Inflammation of the pancreas. "Administration of antiTNFα therapy significantly improved intestinal permeability and pancreatitis and upregulated the IGF2BP3 and CLDN11 expression." (PMID 39856555, 2025).
pilomyxoid astrocytoma (2 papers, 2020 to 2023). An astrocytic tumor of uncertain relation to pilocytic astrocytoma. "IGF2BP3 has previously been associated with genes involved in M-phase and cell cycle regulation in pilocytic/pilomyxoid astrocytomas." (PMID 37760460, 2023).
preeclampsia (2 papers, 2024 to 2025). Preeclampsia is a hypertensive disorder of pregnancy that is characterized by new-onset hypertension with proteinuria presenting after 20 weeks of gestation, and depending on mild or severe forms may initially present with severe headache, visual disturbances, and hyperreflexia. "This multifaceted role highlights IGF2BP3 as a critical molecular mediator in trophoblast biology and underscores its therapeutic potential in managing preeclampsia." (PMID 40563987, 2025). "Following the elucidation of IGF2BP3′s involvement in preeclampsia progression, its impact on HTR-8/SVneo trophoblast cell function was assessed by modulating its expression levels." (PMID 40563987, 2025). "These microRNAs can bind to IGF2BP3 mRNA, leading to its degradation or translational repression, thereby modulating its expression and functional impact across various cellular contexts, including trophoblast development and pathological conditions such as preeclampsia." (PMID 40563987, 2025). "Secondly, while focused on PDE3A as a key downstream effector of IGF2BP3, we acknowledge the emerging significance of apoptotic and autophagic regulators such as BCL-2 and Beclin-1 in preeclampsia and HELLP syndrome." (PMID 40563987, 2025).
retinoblastoma (2 papers, 2024 to 2025). A malignant tumor that originates in the nuclear layer of the retina. "Insulin like growth factor 2 mRNA binding protein 3 (IGF2BP3)-mediated N6-methyladenosine of USP49 enhances carboplatin resistance in retinoblastoma by promoting autophagy through stabilizing Sirtuin 1 (SIRT1)." (PMID 41035649, 2025).
thyroid nodule (2 papers, 2023 to 2025). A small circumscribed mass in the THYROID GLAND that can be of neoplastic growth or non-neoplastic abnormality. "This study confirms that further research assessing RET/PTC and THADA/IGF2BP3 rearrangements in suspicious thyroid nodules is necessary to improve patient management, particularly for deciding if a targeted therapy plan can be developed." (PMID 37444504, 2023). "We included patients who underwent surgery for thyroid nodules that pre-operatively underwent molecular testing showing either RET/PTC or THADA/IGF2BP3 gene fusion." (PMID 37444504, 2023).
abortion (1 paper, 2022). the ending of pregnancy by removing a fetus or embryo before it can survive outside the uterus. "To verify that IGF2BP3 is regulated by TGF-β1 regulation of the maternal–fetal interface cross talk also has effects in murine abortion models, we collected serum from RSA and control mice and measured TGF-β1 expression levels in them using an ELISA kit." (PMID 35465321, 2022). "We used qPCR analysis of first trimester decidual tissues from RSA and control mice to determine whether IGF2BP3 involve in the abortion-prone animal model." (PMID 35465321, 2022).
acral lentiginous melanoma (1 paper, 2022). A form of melanoma occurring most often on the plantar, palmar, subungual, and periungual skin. "Although, in the available literature, IGF2BP3 was mostly studied in acral lentiginous melanomas." (PMID 35565448, 2022).
acute kidney injury (1 paper, 2023). Sudden and sustained deterioration of the kidney function characterized by decreased glomerular filtration rate, increased serum creatinine or oliguria. "We found that IGF2BP3 was mainly upregulated in CKD, and little or no induction of IGF2BP3 was observed in animal models of acute kidney injury (AKI) at 3 days after cisplatin or 1 day after IRI, suggesting that it could be relevant to kidney fibrogenesis but not to renal repair and regeneration." (PMID 36520532, 2023).
amyloid (1 paper, 2020). "The PPP2R2B association remained genome-wide significant after additionally covarying for global amyloid burden and cerebrovascular disease risk, while the IGF2BP3 association was partially attenuated after accounting for amyloid load." (PMID 33426524, 2020).